C2orf74 (chromosome 2 open reading frame 74)
Synonyms: LOC339804
Tractability: Antibody: UniProt predicts a signal peptide or a membrane-spanning region.
Gene: Protein-coding gene on chromosome 2 (61,145,068 to 61,164,828, forward strand). Ensembl gene ENSG00000237651.
Subcellular location: Membrane
Subcellular location (Human Protein Atlas): Centrosome
Gene Ontology:
Molecular function: protein binding
Cellular component: membrane
Genetic constraint (gnomAD): Loss-of-function variants: 11 observed, 16.05 expected, observed/expected ratio (o/e) 0.69, 90% interval 0.43 to 1.13. The upper end of that interval is the gene's LOEUF score, 1.13, which puts it in group 4 of 6, group 1 being the genes least tolerant of losing a copy. Missense variants: 205 observed, 218.47 expected, observed/expected ratio (o/e) 0.94, 90% interval 0.84 to 1.05. Synonymous variants: 72 observed, 69.56 expected, observed/expected ratio (o/e) 1.04, 90% interval 0.86 to 1.26.
Homologues: Orthologues: chimpanzee C2AH2orf74 (100% identical), macaque C13H2orf74 (95% identical), dog C2orf74 (66% identical), rabbit C2orf74 (63% identical), pig C2orf74 (59% identical), mouse 1700093K21Rik (56% identical), rat C14h2orf74 (52% identical).
Diseases named in the same sentence as C2orf74 in open-access papers:
C2orf74 is named in the same sentence as 5 diseases in open-access papers, as found by Europe PMC text mining. Sharing a sentence is not in itself a finding about the gene and the disease. The quoted sentences say what the papers report.
breast carcinoma (1 paper, 2021). "Of the remaining 12 genes, seven (A4GALT, C2ORF74, HRCT1, ZC4H2, ZNF512, ZNF655, and ZNF608) show similar relative expression profiles in large patient samples and other breast cancer cell lines thereby giving insight into predicted role of H3K4me3 mediated gene regulation via the miRNA-mRNA axis." (PMID 34261302, 2021).
leukemia (1 paper, 2023). A malignant (clonal) hematologic disorder, involving hematopoietic stem cells and characterized by the presence of primitive or atypical myeloid or lymphoid cells in the bone marrow and the blood. "Over-representation analysis shows the related GO terms for both ORF proteins in each pair: ‘GO:0016311~dephosphorylation’ and ‘GO:1903293~phosphatase complex’ (C2orf74 and C20orf27) as well as ‘PA444750~leukemia’ and ‘PA444761~ leukemia, myeloid’ (C5orf24 and C16orf71)." (PMID 37373333, 2023).
sarcoidosis (1 paper, 2025). Sarcoidosis is a multisystemic disorder of unknown cause characterized by the formation of immune granulomas in involved organs. "Among them, there were 14 genes (ABT1, BTN2A2, C2orf74, CCDC88B, FAM213A, MDH2, METTL21B, PRSS16, RP3-473L9.4, TCF19, TSFM, UBASH3A, UQCC2, ZSCAN26) associated with sarcoidosis risk consistently across these tissues." (PMID 40075078, 2025). "In addition, our TWAS pinpointed many tissue-specific sarcoidosis-associated genes and found expressions of 14 genes (ABT1, BTN2A2, C2orf74, CCDC88B, FAM213A, MDH2, METTL21B, PRSS16, RP3-473L9.4, TCF19, TSFM, UBASH3A, UQCC2, ZSCAN26) associated with sarcoidosis across all three target tissues." (PMID 40075078, 2025).
C2orf74 also shares sentences with these, for which no sentence is quoted: cancer (1 paper); tumor (1).